FTO (FTO alpha-ketoglutarate dependent dioxygenase)
Diseases named in the same sentence as FTO in open-access papers (continued):
Sharing a sentence is not in itself a finding about the gene and the disease.
tumor (continued). "Together, our findings highlight the critical role of FTO in CRC metastasis and reveal a novel epigenetic mechanism by which the hypoxic tumor microenvironment promotes CRC metastasis." (PMID 34218271, 2021). "In conclusion, we showed in the current study the abnormal USP18/FTO/PYCR1 signaling network in BLCA tissue, which favors cell proliferation and migration in vitro as well as tumor initiation and progression in vivo." (PMID 33461172, 2021). "Over-expression of FTO was shown to drive LINC00022-dependent cell proliferation and tumor growth of ESCC." (PMID 34544449, 2021). "Downregulated FTO expression substantially increases the m6A modifications on MYC, resulting in the binding of YTHDF1 to promote MYC mRNA translation and tumor cell glycolysis and growth." (PMID 33966037, 2021). "Blockade of FTO is an effective way to sensitize AML cells to T‐cell cytotoxicity by targeting leukocyte immunoglobulin like receptor B4 (LIRB4), which alleviates tumor immune evasion in AML to some degree." (PMID 34586737, 2021). "Our findings uncovered a critical mechanism of epitranscriptome regulation by Wnt/β-catenin-mediated FTO downregulation and underscored the role of m6A modifications of MYC mRNA in regulating tumor cell glycolysis and growth." (PMID 33966037, 2021). "The expression of FTO and YTHDF2 can be influenced by tumor heterogeneity, hypoxia, and post-translational modification." (PMID 33390849, 2021). "In conclusion, our results systematically demonstrated the expression, potential function, and prognostic value of the m6A RNA methylation regulator FTO in STAD, contributing to tumor gene-targeting therapy and clinical prognosis study." (PMID 35299934, 2021). "The tumor cells exhibited a significant increase in the expression of WTAP, YTHDF2, and YTHDF3, but a reduction in the expression of FTO and ALKBH5 compared to the normal epithelial cells in the para-tumor samples." (PMID 34733841, 2021). "The IHC of subcutaneous xenograft tumours showed that the positive rate of CDK6 and Ki-67 increased significantly in the FTO-overexpression group and decreased significantly in the FTO-knockdown group." (PMID 34725345, 2021). "FTO and ALKBH5 act as an m6A demethylase, their inhibitors such as Rhein, meclofenamic acid (MA) and IOX3 have been identified as effective anti-tumor drugs." (PMID 34051847, 2021). "The tumor growth between CAL27‐A‐shFTO and CAL27‐shRNA was comparable, suggesting that FTO silencing significantly reduced the tumor growth rate of CAL27‐A cells." (PMID 34378866, 2021). "To investigate m6A eraser expression in CRC, we first analyzed FTO and ALKBH5 mRNA and protein levels in paired CRC tumor and adjacent normal tissues from Sun Yat-sen University Cancer Center (SYSUCC)." (PMID 34218271, 2021). "FTO depletion and YTHDF1-dependent upregulation of c-Myc promoted tumor cell glycolysis, growth, migration, and invasion and accelerated tumor growth in mice and tumor metastasis to the lung." (PMID 33966037, 2021). "Newly identified specific FTO inhibitors; FB23, FB23-2, CS1, and CS2, are promising for anti-tumor therapy strategies." (PMID 34386490, 2021). "METTL3, VIRMA, and hnRNPC showed higher expression in tumor samples, while METTL14, ZC3H13, FTO, ALKBH5, YTHDF2, YTHDC1, and YTHDC2 showed higher expression in normal tissue samples 53,152,156,157." (PMID 33390849, 2021). "Recently, peripheral blood m6A modifier seems to be a potential noninvasive biomarker for the detection and diagnosis of NSCLC, and down-regulating FTO and ALKBH5 in NSCLC had a great connection with tumor stage and metastasis." (PMID 34345203, 2021). "Further analysis using GEPIA showed that among the three m6A regulators, only FTO was highly expressed in ESCC and was positively correlated with LINC00022 in 182 tumor samples." (PMID 34544449, 2021).
tumor (continued). "A negative correlation was observed between miR-576 and CDK6 expressions (r = −0.75, P < 0.001), whereas a positive correlation was observed between FTO and CDK6 expressions (r = 0.71, P < 0.001) in 20 tumour tissues." (PMID 34725345, 2021). "Especially, FTO (in all of nine tumor types), RBM15 (in seven of nine tumor types), and YTHDF1 (in six of nine tumor types) showed a wide range of inter-group expression differences." (PMID 33585244, 2020). "Five m6A-related genes (ZC3H13, METTL14, YTHDF2, YTHDF3 and HNRNPA2B1) showed significantly downregulated in tumor tissue, while seven regulators (YTHDC2, FTO, WTAP, METTL3, ALKBH5, RBM15 and KIAA1429) was remarkably upregulated in ccRCC." (PMID 32419773, 2020). "Subsequently, they further developed two others promising FTO inhibitors, namely CS1 and CS2, which exhibit strong anti-tumor effects in multiple types of cancers." (PMID 33598423, 2020). "Comparisons between adjacent normal and tumor samples identified seven down-regulated (METTL14, WTAP, YTHDC1, YTHDC2, ALKBH5, FTO, and YTHDF2) and one up-regulated (YTHDF1) regulators." (PMID 32500031, 2020). "In this study, we first performed RT-qPCR and found an upregulation of FTO mRNA expression in CRC tissues and cells compared with the non-tumor tissues and HIEC cells." (PMID 33183350, 2020). "Comparing with the adjacent tissues, the writer (METTL3 and METLL14) expressions were upregulated in tumor tissues of LUAD patients, while the eraser FTO expression was downregulated." (PMID 32195181, 2020). "Control and FTO-knockdown MDA-MB-231 cells were orthotopically injected into mouse mammary gland fat pads, and xenograft tumor growth was monitored accordingly." (PMID 30922314, 2019). "As a tumor suppressive factor and a marker for epithelial phenotype, E‐cadherin changes elicited by METTL14/FTO knockdown were in line with the activation/inhibition of Wnt/PI3K‐Akt pathways." (PMID 31243897, 2019). "Further analysis indicated that, among overexpressed ALKBH proteins, the greatest difference between tumour and surrounding tissue was observed for ALKBH2 (5-fold), FTO (4-fold), ALKBH1 (3-fold), and 5 (2-fold)." (PMID 31519943, 2019). "For instance, inhibition of the RNA demethylase, FTO, suppresses GSC growth and self-renewal, consequently suppressing tumor progression of GBM." (PMID 29439529, 2018). "Suppression of the m6A level, via FTO or ALKBH5 overexpression, promoted proliferation of cervical cancer cells, whereas increasing the m6A level led to significant suppression of tumor development, both in vitro and in vivo." (PMID 29439529, 2018). "Targeting m6A writers (e.g., METTL3, METTL14), erasers (e.g., FTO, ALKBH5), or circRNA–miRNA interactions could restore regulatory balance and mitigate tumor aggressiveness." (PMID 41516402, 2026). "Importantly, silencing FTO mirrored the effects of circGDI2 knockdown, suppressing tumor growth and down-regulating IGF2BP2/PKM2, further supporting the FTO-circGDI2-IGF2BP2-PKM2 axis in HCC progression." (PMID 41439029, 2026). "Moreover, APOE promotes tumor growth and proliferation in PTC through glycolysis, and analysis has shown that the FTO/APOE axis inhibits PTC glycolysis by modulating the IL-6/JAK2/STAT3 signaling pathway." (PMID 40819127, 2025). "Furthermore, FTO-mediated OGDHL m 6A demethylation represses its expression in ccRCC and regulates lipid metabolism, promoting tumor progression through the FTO/OGDHL/TFAP2A/FASN axis." (PMID 40483535, 2025). "Knocking down FTO enhances CD8+ T cell recruitment and bolsters anti-tumor responses." (PMID 40034695, 2025). "Furthermore, the dual roles of RNA modification effectors like FTO and ALKBH5 (which can act as both oncogenes and tumor suppressors) must be considered." (PMID 41373022, 2025).
tumor (continued). "Additionally, studies have shown that the FTO inhibitor FB23-2, when combined with radiotherapy, significantly inhibits tumor spheroid formation and the self-renewal capacity of GSCs, suppresses cell proliferation, and induces apoptosis in GBM cells." (PMID 40823093, 2025). "By analyzing the role of the modification of mRNA and ncRNA in cancer progression, researchers confirmed strong participation, mostly regarding METTL3/METTL14 complex, FTO, and ALKBH5, in tumor cell proliferation, invasion, migration, angiogenesis, metastasis, and drug resistance development." (PMID 41157107, 2025). "We found smokers had a higher FTO expression when compared to their non-smoker counterparts: 58.1% of smokers’ tumor samples showed high FTO expression compared to 18.1% in non-smokers." (PMID 40722726, 2025). "Therefore, inhibiting methyltransferase activity like METTL3 or activating demethylases like FTO or ALKBH5 can reduce m6A modification levels, thereby inhibiting tumor progression and resistance." (PMID 40740874, 2025). "Furthermore, tumor cells utilize glycolysis promoted by FTO to inhibit the activation and effector states of CD8+ T cells, which can be reversed by combining an FTO inhibitor with anti-PD-L1 blockade." (PMID 38902779, 2024). "In urinary system tumors, the main m6A erasers are FTO and ALKBH5, which play a role in the initiation and progression of tumors, affecting tumor proliferation, invasion, migration, drug resistance, glycolytic reprogramming, autophagy, and other malignant behaviors." (PMID 38632251, 2024). "In addition, we identify Mupirocin as a novel inhibitor of FTO, and Mupirocin induces CRC ferroptosis and inhibits tumor growth." (PMID 38600610, 2024). "FTO activates transcription factors by mediating m6A demethylation, increases glycolytic metabolic activity, weakens the function of CD8+ T cells, and promotes tumor growth." (PMID 39033180, 2024). "On the other hand, FTO inhibitor Dac51, a recently discovered FB23 analog, increases CD8 + T cell infiltration and enhances PD-L1 immunotherapy efficacy, generating significant anti-tumor effects." (PMID 39459530, 2024). "This highlights the critical role of the FTO in modulating not just tumor growth but also drug resistance, making it a potential target for improving cancer therapy outcomes." (PMID 39744011, 2024). "In addition, various m6A methylation modulators such as METTL3, FTO, and IGF2BP have been found to have some relationship with tumor prognosis." (PMID 39033180, 2024). "Mechanistically, FTO inhibits phosphodiesterases 4B (PDE4B) and 1C (PDE1C) via demethylase activity via m6A modification, resulting in cAMP accumulation and reduced stemness in OC and tumor initiation." (PMID 38544837, 2024). "The demethylase FTO has been shown to be responsible for decreasing m6A methylation of Apolipoprotein E (APOE) mRNA and modulating the IL-6/JAK2/STAT3 signaling pathway, thereby inhibiting tumor glycolysis and abrogating tumor growth." (PMID 38902779, 2024). "However, relatively few studies have investigated the regulatory mechanisms of FTO and ALKBH5 in tumor development and angiogenesis." (PMID 39295872, 2024). "Furthermore, the protein translation process of estrogen receptor alpha (ERα), another target of FTO, is suppressed due to the increased m6A levels on its mRNA, consequently inhibiting CCA tumor growth." (PMID 38365891, 2024). "Thus, we first examined the expression levels of METTL3, METTL14, WTAP, RBM15, FTO, and ALKBH5 transcripts in tumor samples and corresponding normal samples using the GEPIA database." (PMID 38665783, 2024). "FTO is increased in acute myeloid leukemia, and regulates the ASB2 and RARA levels by demethylating the m6A modification on their RNA, leading to elevated tumor proliferation and reduced apoptosis." (PMID 39457524, 2024).
tumor (continued). "Similarly, in OSCC, downregulation of FTO and overexpression of METTL14 enhanced autophagy while inhibiting cell proliferation, migration, invasion, and tumor growth." (PMID 38576024, 2024). "AURKB, as a downstream key node of the FTO/SP1/AURKB pathway, could influence the tumor microenvironment of GC." (PMID 38956367, 2024). "The presence of FTO promotes the metastasis and spread of HCC, and inhibition of its activity can alter the cell cycle and affect the demethylation of glycolytic pyruvate kinase isoenzyme PKM2 to inhibit tumor development." (PMID 39033180, 2024). "Interestingly, we develop Mupirocin as a novel inhibitor of FTO and Mupirocin induces CRC ferroptosis and inhibits tumor growth, as well as enhances the anti-tumor effects of Erastin or RSL3." (PMID 38600610, 2024). "Additionally, substrate-competitive FTO inhibitors such as FB23-2 and Dac51 have been effective in promoting apoptosis in AML cells and reactivating CD8+T cells by inhibiting tumor glucose metabolism, respectively." (PMID 38902779, 2024). "To identify potential FTO inhibitors, which suppress CRC tumor growth by inducing ferroptosis, we conducted a structure-based virtual screening of a small molecule library consisting of 1680 bioactive compounds based on the FTO crystal structure (PDB code: 3LFM)." (PMID 38600610, 2024). "ALKBH5 and FTO act as double-edged swords, which are upregulated in BC and AML and can exert pro-oncogenic effects by regulating mRNAs with transcription factors, but FTO is tumour suppressive for GBM." (PMID 38711100, 2024). "Together, these results demonstrate FTO and ALKBH5 inhibits tumor growth in vivo and may participates glucose metabolism." (PMID 37580808, 2023). "In conclusion, FTO is downregulated in TC compared with the adjacent nontumor tissues and inhibits tumor progression." (PMID 37915103, 2023). "In oral squamous cell carcinoma, after FTO knockdown, YTHDF2 binds with eIF4G1 transcripts containing m6A, resulting in mRNA degradation and downregulating the expression of eIF4G1 protein, thereby activating autophagy and suppressing tumor growth." (PMID 36632456, 2023). "Moreover, FTO and ALKBH5 negatively regulated METTL3 and positively regulated METTL14 expression levels, enhancing their role as tumor suppressors of CRC." (PMID 37580808, 2023). "Glutaminolysis blockade enhanced FTO expression and disrupted YTHDF2-mediated RNA decay of activating transcription factor 4 (ATF4), stimulating autophagy activation and compromising anti-tumour efficacy." (PMID 36859310, 2023). "However, the inconsistent roles of FTO and ALKBH5 in RCC are most likely due to the neglect of tumor heterogeneity, different RCC subtypes, or enzyme interaction." (PMID 38117350, 2023). "The study demonstrated that FTO targets m6A in the 3′UTR region of the pro-apoptotic BNIP3 mRNA, suggesting FTO as a potential therapeutic target to enhance BNIP3 expression and decrease tumor growth and metastasis." (PMID 37369946, 2023). "Additionally, inhibitors against FTO, ALKBH5, IGF2BP1, and ADAR1 have shown promising anti-tumor properties in vitro and in vivo." (PMID 38071304, 2023). "Moreover, FTO and ALKBH5 function as tumor suppressors by inhibiting METTL3 while promoting METTL14 expression." (PMID 37580808, 2023). "As a tumor suppressor in HCC, the guanine nucleotide-binding protein G(o) subunit alpha (GNAO1) is a m6A downstream target of FTO, and SIRT1-mediated ablation of FTO downregulates GNAO1 mRNA expression through increasing m6A modification." (PMID 37391814, 2023). "The mRNA expression levels of YTHDC2, YTHDF1, YTHDF3, IGF2BP1, and IGF2BP3 were significantly increased in tumour tissues compared with paired normal breast tissues, while the METTL14, WTAP, FTO, and IGF2BP2 expression levels were significantly decreased in tumour tissues." (PMID 36632454, 2023).
tumor (continued). "In addition, several studies have reported the potential tumor-promoting or tumor-suppressing effects of m6A methylation-related factors such as METTL3, METTL14 and FTO in PCa." (PMID 37033963, 2023). "The increased FTO strengthens the stability of ZEB1 mRNA transcripts, which results in chemoresistance and epithelial-mesenchymal transition of tumor cells, indicating neutrophils control tumor progression by impacting the RNAs regulators in tumor cells." (PMID 37928272, 2023). "Notably, FTO-induced hypomethylation drives the downregulation of SLC7A11 expression, promoting tumour ferroptosis." (PMID 36859310, 2023). "Stable knockout of FTO inhibited OSCC cell viability, colony formation, and tumor growth." (PMID 36793593, 2023). "IHC assay indicated that there were significant correlations between FTO expression and several clinicopathological features, such as tumor size, metastasis, and TNM stage, but not with gender and age." (PMID 35311620, 2022). "FTO, RBMX, METTL3, and METTL14, have been demonstrated to be tumor proto-oncogenes or biomarkers through m6A, with METTL3 serving as a pathological diagnostic index and potential therapeutic target for ESCA, and with RBMX encoding HNRNPG to affect m6A, also a member of the hnRNPs family." (PMID 36195940, 2022). "It is under speculation that the regulation of SLC7A11 gene expression may be a crucial target of FTO in modulating PTC cell ferroptosis and tumor progression." (PMID 35721711, 2022). "The RNA demethylases FTO and ALKBH5 are also crucial in tumours." (PMID 35518355, 2022). "Regulating the expression of SLC7A11 gene is believed to be a critical, but not the sole, target for FTO to regulate tumor progression and ferroptosis in PTC cells." (PMID 35721711, 2022). "FTO can decrease HOXB13 mRNA decay and increase HOXB13 protein expression, promoting Wnt signaling pathway activation and the expression of downstream proteins, leading to tumor metastasis and invasion." (PMID 35813486, 2022). "Therefore, we conclude that m6a-related mRNAs, especially METTL14, IGFBP2, and FTO, can influence the clinical outcome of HCC by altering tumor cell proliferation and survival." (PMID 35734590, 2022). "FTO-mediated m6A methylation of PKM2 promotes HCC progression by accelerating the generation of translation products and conversely, FTO knockdown induces G0/G1 phase blockage and inhibits tumor proliferation and growth in vivo." (PMID 35794625, 2022). "The upregulation of FTO further strengthens ZEB1 transcripts stability and expression by decreasing N6-methyladenosine (m6A) RNA methylation, leading to chemoresistance and epithelial-mesenchymal transition (EMT) of tumor cells." (PMID 36302751, 2022). "We briefly investigated the m6A erasers ALKBH5 and FTO in a dataset including survival data and found that ALKBH5 might play a more prominent role in tumor suppression." (PMID 35517412, 2022). "Moreover, the small molecule inhibitor FB23-2 targeting FTO inhibited tumor growth and prolonged survival in the patient-derived xenograft (PDX) model mice, suggesting that FTO is a potential effective therapeutic target for ccRCC." (PMID 36263177, 2022). "FTO expression was evidently increased in tumor stem-like cells (P < 0.05); however, there was no significant change in the expression level of ALKBH5 (P > 0.05)." (PMID 35568876, 2022). "Between 2020 and the present, several upgraded FTO inhibitors have been developed, including CS1/CS2 and Dac51, which not only suppress cancer cell proliferation and cancer stem cell self-renewal but also improve anti-tumor immunity." (PMID 35296338, 2022). "Further, we also found the m6A methylation-related genes FTO, IGF2BP3, and YTHDC1 might participate in the process of PGM1 methylation modification, thereby affecting tumor progression and metastasis." (PMID 35251177, 2022).